IL1B (interleukin 1 beta)
Diseases named in the same sentence as IL1B in open-access papers (continued):
Sharing a sentence is not in itself a finding about the gene and the disease.
diabetes (continued). "In our study, the expression of IL-1β in rats with telmisartan plus STZ treatment was significantly lower than that in rats with only STZ treatment, suggesting the blockade of RAS may increase the resistance to STZ-induced diabetes partially through the alleviation of inflammatory damage." (PMID 23197974, 2012). "The time course of GFAP, α2-macroglobulin, and ceruloplasmin overexpression in the retina of diabetic rats was similar to that of IL-1β with no changes as compared to control rats at 1.5 months from the induction of diabetes and a significant upregulation after 3 months of diabetes." (PMID 22615852, 2012). "Subgroup analyses showed that the post-ACS upregulation of NLRP3, caspase-1, and IL-1β was consistent across STEMI and NSTEMI presentations and was not significantly modified by diabetes status." (PMID 41598157, 2025). "Interestingly, although IL1B expression is significantly elevated in the visceral adipose tissue of obese patients, its levels are not directly correlated with diabetes status, suggesting that IL1B may independently initiate metabolic inflammation, separate from diabetes." (PMID 40661082, 2025). "There is reduction in pro-inflammatory markers like hsCRP, IL-6, IL-1β, TNF-α, and IFN-γ in patients with diabetes and in vitro models without diabetes, while there is a change in polarity from M1 to M2 macrophages when treated with SGLT2i." (PMID 40868177, 2025). "The Canakinumab Anti-Inflammatory Thrombosis Outcomes Study (CANTOS) demonstrated that canakinumab, an IL-1β inhibitor, effectively lowered MACE rates in patients with or without diabetes." (PMID 37762961, 2023). "Serum IL-1β levels were significantly increased in patients with diabetes and PAD compared with both healthy controls and subjects with diabetes without PAD." (PMID 36674682, 2023). "Nonetheless, in a secondary analysis of the diabetes endpoint in the CANVOS trial, blockade of IL-1β with canakinumab over a median period of 3.7 years did not reduce incident diabetes." (PMID 38124083, 2023). "In contrast, unlike glucocorticoids, diabetes treatment with high-dose salicylates, anti-cytokine antibodies (TNF and IL1β) or gene therapy approaches targeting NF-κB regulatory loops (e.g. A20) do not risk directly inhibiting basal NF-κB activity." (PMID 37311878, 2023). "When the inflammatory parameters were re-evaluated according to the presence of concomitant diabetes, lower levels of IL-18 and hsCRP were detected in the presence of diabetes, but no significant change was observed in the NLRP3 and IL-1β levels." (PMID 37763063, 2023). "Diabetes markedly reduced T-GSH, NP-SH, CAT and SOD, while TBARS, TNF-α and IL-1β levels were increased in the diabetic testis compared to non-diabetic controls." (PMID 26122042, 2015). "At variance with IL-1β, the retinal expression of IL-6 and TNF-α was not changed in diabetes at any of the time points tested." (PMID 22615852, 2012). "Lack of TNFα increased higher basal VCAM-1 protein and sVCAM-1, but failed to up-regulate IL-6 and IL-1β mRNA and VCAM-1 protein in response to diabetes." (PMID 20856927, 2010). "In vivo, Pn@Janus TPP implantation markedly enhanced alveolar bone regeneration in a diabetic rat periodontitis model, restored periodontal architecture, and reduced the expression of key pro-inflammatory cytokines (IL-6, TNF-α, iNOS, IL-1β), without inducing systemic toxicity." (PMID 41704297, 2026). "Therefore, the purpose of the study was to determine the mRNA expression levels of mTOR, Foxp3, IL1β, and IL17A genes in rat parapancreatic adipose tissue with experimental streptozotocin-induced diabetes mellitus, with or without metformin administration." (PMID 32341701, 2020). "However, the involvement of IL-1β and TNF-α of Kupffer cells in diabetes-enhanced liver abscess has not been clarified." (PMID 28493939, 2017).
diabetes (continued). "Furthermore previous studies have shown higher IL-1β and PGE2 crevicular fluid levels in subjects with either type 1 or type 2 diabetes than in subjects without diabetes, regardless of periodontal status." (PMID 29075409, 2017). "Already after 4 weeks of diabetes, a time-point when no changes in aortic plaque size had yet occurred, expression of VCAM-1, MCP-1, IL-1β, Cox2, TF and maybe also IL-6 and ICAM-1 (borderline significance) were higher than in control non-diabetic mice." (PMID 23755169, 2014). "In the present study we found that TNFα−/− deficient mice exhibited higher basal levels of VCAM-1 protein in retinal vessels and sVCAM-1 in plasma than wt mice, but these mice failed to up-regulate IL-6 and IL-1β mRNA and VCAM-1 protein in response to diabetes." (PMID 20856927, 2010). "By demonstrating an EMPA-mediated inhibition of IL-1β-induced SGK1 expression, this effect might be a potential explanation for the positive clinical effect seen with the use of SGLT2i in CKD patients irrespective of the presence and absence of diabetes." (PMID 34064989, 2021). "One study in type 2 diabetes mellitus (T2DM) patients demonstrated that Propolis at a dose of 1000 mg/ day administration for 3 months, significantly decreased hs-CRP and TNF-α levels but had no significantly difference seen for the serum IL-1β and IL-6 levels." (PMID 32817750, 2020).
periodontitis (903 papers, 2007 to 2026). An acute or chronic inflammatory process that affects the tissues that surround and support the teeth. "Such heterogeneity is consistent with findings in periodontitis, where IL-1α and IL-1β polymorphisms show population-specific associations influenced by ethnic background and environmental exposure." (PMID 41373620, 2025). "In fact, in a Turkish population, heterozygosity for allele 1 of IL-1α (+4845) or homozygosity for allele 1 of IL-1β (+3954) increases vulnerability to localized aggressive periodontitis." (PMID 41300760, 2025). "IL‐1β is a major cytokine associated with the progression of periodontitis, as it enhances osteoclast formation and promotes bone resorption." (PMID 41298339, 2025). "This is because elevated levels of IL-1β have been significantly associated with the immunopathology of periodontitis, promoting the destruction of periodontal tissue, especially through alveolar bone resorption and damage to the lamina propria." (PMID 41009326, 2025). "These cytokines (such as TNF‐α, IL‐6, IL‐1β, and IL‐17) play a role in the bone destruction pathway of periodontitis and can cause bone resorption by regulating osteoclast formation." (PMID 40761494, 2025). "Cells were treated with IL‐1β (10 ng/mL), a pro‐inflammatory cytokine implicated in the progression of periodontitis or with 1% FBS, used here as a surrogate for tissue injury." (PMID 40346842, 2025). "The discovery of IL-1β as an independent predictor of candidiasis is significant, as this cytokine has been repeatedly linked to the progression from gingivitis to periodontitis." (PMID 41301927, 2025). "Salivary IL-1β levels increase progressively from gingivitis to Stage II–III periodontitis, indicating its diagnostic relevance in periodontal disease progression." (PMID 41440349, 2025). "IL-1β levels correlated with probing depth (PD) and attachment loss (AL) across various stages of periodontitis." (PMID 41440367, 2025). "Regarding periodontal disease, a study involving 186 periodontitis patients and 208 control subjects demonstrated an association between IL1B gene polymorphisms and susceptibility to PD." (PMID 40857330, 2025). "Several candidate gene studies have investigated IL-1 polymorphisms (notably IL1A −889 and IL1B +3954/rs1143634) in relation to periodontitis." (PMID 41300760, 2025). "As previously reported, activity levels of the salivary biomarkers MMP-8, MMP-9, and IL-1β have been linked to periodontitis." (PMID 41002732, 2025). "Certain bacteria in subgingival plaques appear to be minimally affected by the factors associated with gingivitis and periodontitis, despite most bacteria exhibiting correlations with IL-1β, endotoxins, TLR-SEAP, TLR-ATP, PAD, MMP-1, MMP-9, GBI, and MGI." (PMID 41303313, 2025). "TIFA activation of the NF-κB signaling pathway has been implicated in periodontitis in diabetic mice, with increased expression of IL-1β and IL-18." (PMID 40385253, 2025). "In our experiments, we observed elevated levels of serum pro-inflammatory cytokines (IL-17A, IL-1β, IL-6, IL-8) associated with periodontitis." (PMID 40732209, 2025). "Although the frequency of periodontitis was similar in all groups, higher IL-6 (p = 0.004), IL-1β (p = 0.002), and IL-33 (p = 0.006) levels were associated with poor periodontal status." (PMID 40008732, 2025). "On the contrary, the vulnerability to localized aggressive periodontitis in Chinese populations has been associated with polymorphism at IL-1β (−511)." (PMID 41300760, 2025). "IL-1β remains one of the most promising salivary biomarkers for early periodontitis detection, although its association with T1DM is inconsistent." (PMID 41280935, 2025). "After adjusting the effect of age, an increased salivary level of IL-1β was found to be associated with an increased probability to have periodontitis (odd ratio = 1.033; p = 0.004)." (PMID 39445112, 2024).
periodontitis (continued). "This suggests that Pepper Elder extract effectively reduces the levels of TNF-α and IL-1β, mitigating tissue damage and alveolar bone loss, which are hallmark features of periodontitis." (PMID 39539670, 2024). "IL1B rs1143634 is the most reported genetic variation linked to an elevated susceptibility to the progression of periodontitis." (PMID 38248068, 2024). "This significant correlation highlights the essential function of IL-1β in the host immune response related to periodontitis, particularly in patients with identified IL-1β gene variants." (PMID 39445112, 2024). "In a study of lcSSc patients, periodontitis was found in 31 of 38 patients, and in these, an IL-1β polymorphism (C3953 allele) was linked to the presence of pathogenic P. intermedia bacteria." (PMID 38779873, 2024). "In a rat model of periodontitis, drug inhibition of Caspase-4 or IL-1β antibody significantly reduced alveolar bone loss and periodontal soft tissue injury." (PMID 38191432, 2024). "According to another research, ET-1 controls theexpression of IL-1β in gingival tissues.Although its precise effects are unclear, ET-1 is increased in periodontitis and is linked to inflammatory cytokines among othervariables." (PMID 39917223, 2024). "CXCL8 has been reported to be overexpressed in carious lesions, and a genetic variant of IL1B has been associated with caries susceptibility, and both have been reported as therapeutic targets of curcumin in periodontitis." (PMID 38920854, 2024). "IL-1α (rs1800587) and IL-1-β (rs1143634) polymorphisms have been correlated to generalized aggressive periodontitis." (PMID 39057807, 2024). "The pro-inflammatory cytokine known as interleukin-1 beta (IL-1B) plays a significant role in the development of periodontitis by causing inflammation, bone resorption, and the breakdown of periodontal tissues." (PMID 38248068, 2024). "IL-1β +3954 gene polymorphism is associated with periodontitis and is expected to be among the several causes of respective pathology." (PMID 38759999, 2024). "In Caucasians, the polymorphisms IL-1A −889T/C and IL-1B 3953/4 C/T are associated with chronic periodontitis." (PMID 39684335, 2024). "IL-1β and IL-10 have great diagnostic capabilities when used separately or in combination for the diagnosis of periodontitis." (PMID 39445112, 2024). "They concluded that hyperglycemia is independently associated with high GCF IL-1β levels (after adjusting for age, gender, and periodontal clinical parameters) in patients with type 2 diabetes and periodontitis." (PMID 39337292, 2024). "Among the interleukins released during inflammatory processes, IL-6, IL-8, and IL-1β have been widely explored in periodontal medicine for their possible joint pathogenic involvement in periodontitis and other systemic inflammatory conditions." (PMID 38877442, 2024). "Endothelin-1 (ET-1) and interleukin-1β (IL-1β) is increased in periodontitis and is linked to inflammatory cytokines amongother variables." (PMID 39917223, 2024). "This strip enables simultaneous detection of three biomarkers associated with periodontitis—namely, interleukin-1 beta (IL-1β), tumor necrosis factor-alpha (TNF-α), interleukin-8 (MPP-8), and interleukin-1 beta (GCF)." (PMID 38183090, 2024). "The CRS index had a strong association with moderate to severe periodontitis, similar to the determination of the presence of P. gingivalis with IL-1β and PGE2 levels." (PMID 39684335, 2024). "Inflammatory markers such as cytokines for example, IL‐1β, IL‐6, which are elevated in saliva and gingival crevicular fluid, have been implicated in both periodontitis and OSA." (PMID 38433299, 2024). "Second, the innate immune dysregulation in SLE patients with overactive phagocytic cells leads to elevated production of pro-inflammatory cytokines, such as interleukin (IL)-1β and IL-18, which are implicated in the pathogenesis of periodontitis." (PMID 38629069, 2024).
periodontitis (continued). "In the current study, the diagnostic precision of salivary MMP-8 and IL-1β as indicators of gingivitis and periodontitis was evaluated." (PMID 38086426, 2024). "IL-1β, IL-10, and IL-1β/IL-10 had significant diagnostic accuracy for differentiating healthy control from unstable periodontitis (AUCs = 0.99, 0.96, and 1; sensitivity = 0.98,1, and 1; specificity = 0.95, 0.95, and 1, respectively)." (PMID 39445112, 2024). "Tacrolimus, a calcineurin inhibitor, has been demonstrated to protect against the inflammation-induced tissue and bone loss associated with periodontitis in experimental rats and oral diseases through a mechanism involving IL-1β, TNF-α, and IL-6." (PMID 37435641, 2024). "This study focused on measuring the pro-inflammatory cytokines TNF-α, IL-1β, IL-6, and IL-8, pivotal not only in periodontitis but also in cancer-associated chronic inflammation." (PMID 38612423, 2024). "IL1B+3954(T) in the genome not only associates with severe periodontitis but also predicts a weak GCF response in this experimental gingivitis study." (PMID 37762554, 2023). "Conversely, the concurrent presence of all three ‘red’ complex periodontal pathogens and IL1B+3954(T) associated with the greatest IL-1β expression in GCF from periodontitis sites." (PMID 37762554, 2023). "TNF-α, a cytokine secreted by macrophages, has activity like IL-1B and is linked to the tissue destruction process caused by periodontal disease and its presence in saliva is more associated with patients with periodontitis than healthy patients (P =0.0004)." (PMID 37026605, 2023). "The statistical analysis shows that IL-6 and nitric oxide were the biomarkers that showed the greatest value of significant association with periodontitis (P < 0.00001), accompanied by IL-1B (P < 0.0001), TNF-α (P = 0.004) and osteoprotegerin (P = 0.01)." (PMID 37026605, 2023). "As the expression level of IL-1β in periodontal tissue and gingival cervical fluid is directly associated with the severity of periodontitis, regulating IL-1β expression is critical in developing a strategy for the prevention and treatment of periodontitis." (PMID 37238962, 2023). "IL-1β manages the prostaglandin E2 production associated with hard tissue breakdown induction in periodontitis." (PMID 37355561, 2023). "Taken together, our results agree with previous data establishing an association between higher salivary IL-1β levels and the clinical status and higher presence of periodontitis in grade C periodontitis patients." (PMID 36769650, 2023). "Mice with Synoviolin deficiency in myeloid cells had more severe periodontitis and upregulated IL‐1β and IL‐18." (PMID 37506160, 2023). "The conflicted genotype reduces the accuracy with which IL1B+3954(T) alone can associate with periodontitis." (PMID 37762554, 2023). "Among them, only Ifi204, the murine homolog of human IFI16, showed consistent inhibition of expression in the DeP and CgP, which regulates the release of IL-1β in tissues and plays a vital role in bone loss in experimental periodontitis." (PMID 37008900, 2023). "The association with periodontitis was reported and confirmed for IL1B+3954(T) in a study using 117 periodontitis patients and 175 controls." (PMID 37762554, 2023). "The alternate thymidine (T) residue at IL1B+3954 (numbered downstream from the first nucleotide encoding its IL1β protein) is associated with many inflammatory diseases, including periodontitis where periodontopathogens enhance IL-1β expression." (PMID 37762554, 2023). "Cytokines that are frequently associated with periodontitis are IL-1β, IL-6, IL-12, IL-16, IL-17, IL-21, and TNF-α." (PMID 37106750, 2023). "Since the presence of heterogeneity, we adopt the results of the random-effect IVW effects model, which does not identify causal relationship between genetically predicted periodontitis and IL1b." (PMID 36793899, 2023).